IL1B (interleukin 1 beta)
Diseases named in the same sentence as IL1B in open-access papers (continued):
Sharing a sentence is not in itself a finding about the gene and the disease.
colitis (continued). "After three cycles of DSS administration, mice with colitis showed reduced colon length (a marker of intestinal inflammation) as well as increased levels of DAI, MDA (a measure of the colonic oxidative insult), MPO (an index of neutrophil accumulation), and inflammatory factors (IL-1β and IL-6)." (PMID 34393786, 2021). "Our data suggest that decreased IL-1β is not important for GSDMD-mediated colitis promotion." (PMID 34721422, 2021). "Moreover, NLRP3 inflammasome-derived IL-1β and IL-18 play a protective role against oxazolone-induced colitis, and a hyperactive NLRP3 inflammasome (such as that in the Nlrp3 R258W mutant mouse line) confers strong resistance to experimental colitis/CRC." (PMID 34064909, 2021). "Therefore, we analyzed the secreted pro-inflammatory cytokines in colonic tissue of mice and found that the DSS-induced increased secretion of IL-6, IL-1β, and TNF-α was significantly reduced by saffron (20 mg/kg), reducing the severity of the DSS-induced colitis." (PMID 34199466, 2021). "The majority of published studies performed using the experimental models of colitis have indicated that the altered immune response was correlated with the increasing release of pro-inflammatory cytokines, including IFN γ, TNFα, IL-6, IL-1β, GM-CSF, and IL-17A." (PMID 34970585, 2021). "We demonstrated that both extracts, when administered orally, could reduce the elevated levels of pro-inflammatory cytokines, including TNF-α, IL-1β, and IL-6, in the Dextran Sodium Sulfate (DSS) colitis mouse model and effectively ameliorated the experimental colitis." (PMID 34940701, 2021). "Macroscopic and microscopic colitis in sedentary SD mice was accompanied by a significant decrease in CBF, and a significant increase in the colonic expression of tumor necrosis factor-alpha (TNF-α), IL-6, IL-1β and leptin mRNAs and decrease in the mRNA expression of adiponectin." (PMID 33557311, 2021). "Similarly, in the present study, we also found that the levels of serum IL-1β, IL-6, and TNF-α were increased in DSS-induced colitis, while LSE supplementation could decrease these inflammatory cytokines." (PMID 35059326, 2021). "Furthermore, a rat model of DSS-induced colitis exposed to 8 mg/kg of deoxynivalenol in their diet for 4 weeks induced a more rapid and severe onset of colitis than controls and induced significant increases in pro-inflammatory markers (myeloperoxidase, CXCL-1, and IL-1β)." (PMID 33927703, 2021). "In addition to IL-6 and IL-1β, earlier studies reported TNF-α-induced epithelial barrier dysfunction in rat colon via downregulation of occludin and E-cadherin and in DSS-induced colitis in mice." (PMID 33669494, 2021). "For colitis, mainly EPS and extracellular vesicles, but also lactate, they have been described to have an anti-inflammatory role against a variety of acute inflammatory insults: DSS (dextran sulfate sodium), TNFα, FliC (flagellin), IL-1β, and TNBS (2,4,6-trinitrobenzene sulfonic acid)." (PMID 34745425, 2021). "In addition, magnolol restrained the expression of TNF-α, IL-1β, and IL-12 via the regulation of NF-κB and peroxisome proliferator-activated receptor-gamma (PPAR-gamma) pathways and played protective effects on DSS-induced colitis." (PMID 34159200, 2021). "Supplementation of taxifolin significantly inhibited the secretions of tumor necrosis factor-α, interleukin (IL)-1β, and IL-6 and significantly increased the secretions of IL-10, secretory immunoglobulin A, superoxide dismutase, and immunoglobulins (IgA, IgG, and IgM) in DSS-induced colitis mice." (PMID 33664740, 2020). "In contrast, IL-1β, but not IL-1α, activates IL-6 expression in neurons, selectively mediates the response to vascular injury, while IL-1α- and IL-1β-specific actions have also been identified in acute colon inflammation in mice." (PMID 32468079, 2020). "Finally, DSS-induced colitis increased IL-1β secretion compared to the healthy group, and this was not attenuated by the Emmental cheese intake." (PMID 32156075, 2020).
colitis (continued). "Furthermore, vagotomy did not affect Paenalcaligenes hominis-induced colitis; specifically, it did not inhibit colon shortening, myeloperoxidase activity, and IL-1β expression or alter NF-κB+/CD11c+ cell populations." (PMID 32669127, 2020). "In this context, severity of DSS-colitis intestinal inflammation is significantly worsened in mice treated with deoxycholic acid enema but is alleviated by the blockage of S1PR2 as well as inhibition of cathepsin B release, in turn reducing mature IL-1β production." (PMID 33603741, 2020). "Severe colitis in HSD-fed mice was accompanied by a massive increase in neutrophils in colon tissue, increased anti-CD3/anti-CD28-stimulated production of IL-17 in mesenteric lymph nodes, and increased Tnfa expression and IL-6 and IL-1β production in the colonic tissue." (PMID 33339337, 2020). "In particular, it was reported in murine DSS colitis that the activation of A3AR, expressed in colonic epithelia, exerts anti-inflammatory activity through the inhibition of the pro-inflammatory cytokine TNF and IL-1β via the inhibition of the NF-κB signaling pathways." (PMID 32575844, 2020). "Similarly, DMF diminished the expression of NF-κB p65, IL-1β, and TNF-α in experimental colitis." (PMID 32344663, 2020). "Soybean-derived dipeptides and tripeptides decreased the colonic expressions of proinflammatory IFNG, IL-1B, IL-12B, TNF, and IL-17A and MPO activity and increased Foxp3 expression and CD4+CD25+ T cells; therefore, the colon and ileum inflammation of piglets with DSS-induced colitis was attenuated." (PMID 32963495, 2020). "In our study, the level of IL-1β was also significantly lower in rats from the CβGl+ group in comparison to the level observed in the CβGh+, but the highest concentration was noted in the non-supplemented colitis group (CβG−)." (PMID 31590413, 2019). "During the onset of DSS-induced colitis, CD14/TLR4:LPS-dependent interaction between macrophages and bacteria, which have passed through DSS-injured colonic epithelium, results in the activation of NLRP3 inflammasome, which leads to the enhanced production of IL-1β in colonic macrophages." (PMID 31336879, 2019). "Serum interleukin (IL)-12 concentration correlated with colitis activity but IL-1β and TNF did not." (PMID 31172380, 2019). "Indeed, GSK343 administration led to a profound decrease in the levels of pro-inflammatory cytokines, including IL-6 and IL-1β, whereas the levels of TNF-α and IL-17A remained unaffected, indicating that GSK343 treatment reduces the inflammatory response during DSS-induced colitis." (PMID 31160593, 2019). "PXR activation by PCN is protective against DSS-induced colitis due to the activation of phase II enzymes and cellular efflux transporters, such as GSTa1, MDR1a, and MRP2, which alleviates the expression of the proinflammatory cytokines IL-6, TNF-α, ΜCP-1, and IL-1β." (PMID 30804707, 2019). "In addition, blood monocytes produced significantly greater IL-1β but not TNF during DSS colitis when stimulated with LPS, suggesting this pro-inflammatory potential is enhanced even before leaving the blood." (PMID 30542349, 2018). "Further, although mice treated with IL-1β neutralising antibodies display reduced DSS inflammation and expression of IL-6 mRNA transcripts, TNF levels are unaltered, indicating that IL-1β may play a more dominant role in promoting DSS colitis than TNF." (PMID 30542349, 2018). "Using a model of DSS-induced colitis, there is evidence to the antioxidant and anti-inflammatory abilities of ZnOnps in suppressing ROS and malondialdehyde (MDA) production, increasing GSH levels, and suppressing proinflammatory cytokines IL-1β and TNF-α and myeloperoxidase." (PMID 30258848, 2018). "Thus, the DSS-induced colitis resulted in an increase in MPO, INF-γ, IL6, IL1-β, TNF-α, and IL10." (PMID 28528363, 2018).
colitis (continued). "Therefore, we confirmed that oroxylin A could down-regulate the activation of NLRP3 inflammasome, with decreased levels of caspase-1, IL-1β and NLRP3 in colon samples of DSS-induced colitis mice." (PMID 28938606, 2017). "Likewise, treatment with fraxinellone, a natural lactone endowed with immunosuppressive activity, significantly reduced weight loss, diarrhea and colonic macroscopic damage, as well as myeloperoxidase, alkaline phosphatase, and colonic TNF, IL-1β, IL-6, and IL-18 levels in DSS-induced colitis mice." (PMID 28179906, 2017). "Although we did not confirm the effect of lentinan in DSS-induced colitis, a well characterized inflammasome-mediated disease, lentinan might block IL-1β and -18 secretion in a colitis model." (PMID 28465544, 2017). "We showed that exogenous IL-1β, as well as exogenous IL-18, improved OXA-induced colitis in WT mice and prevented worsening of colitis in NLRP3−/− mice, strongly suggesting that the NLRP3 inflammasome-derived IL-1β may have an inhibitory effect on OXA-induced colitis." (PMID 27966619, 2016). "Our present study has shown that induction of colitis by DSS leads to a damage and inflammatory infiltration of colonic mucosa and increases mucosal concentration of IL-1β, whereas administration of ghrelin decreases mucosal concentration of IL-1β in rats watered with DSS solution." (PMID 26713317, 2015). "Furthermore, the administration of anti-TNF-α antibody (infliximab) is effective in improving the clinical status of the patients with Crohn’s disease and the injection of anti-IL-6 receptor antibody in mice with colitis resulted in inhibition of IFN-γ, IL1-β mRNA as well as TNF-α secretion." (PMID 25853847, 2015). "In the mild colitis group, the expression of pro-inflammatory cytokines TNF-α, IL-6, IL-1β were increased to about 1.5 folds (p<0.05), and in the severe colitis group IL-6, TNF-α, IL-1β expression were increased to about 3, 2, and 1.5 folds compared to the water group." (PMID 24504372, 2014). "Interestingly, protection by IL-1β is only achieved with administration of low dose IL-1β, and only when given 24 h, but not 30 min, before the induction of colitis." (PMID 23847622, 2013). "Furthermore, while specific blockade of IL-1α leads to amelioration of colitis, administration of IL-1Ra or anti-IL-1β antibodies do not effectively treat DSS colitis." (PMID 23847622, 2013). "Plasma IL-1β also does not increase in acute colitis induced by 3% DSS." (PMID 24386254, 2013). "Such differential licensing may contribute to the selective production of IL-18, but not IL-1β, by epithelial cells during dextran induced colitis." (PMID 23028835, 2012). "Therefore, we think that IL-1β mRNA expression is a key to understand the symptoms especially in an acute phase of colitis rather than IFN-γ mRNA expression." (PMID 23209802, 2012). "Furthermore, Fuzhuan tea crude extract significantly decreased TNF-α, IL-1β and IFN-γ inflammatory cytokines’ levels, and significantly reduced myeloperoxidase activity, nitric oxide, and malondialdehyde levels in colon tissue, thus improving DSS-induced colitis in mice." (PMID 39272608, 2024). "In addition, overexpression of miR‐378a in UmC‐MSC‐EVs suppresses the secretion of IL‐18, IL‐1β and caspase‐1 cleavage target by reducing NLRP3 inflammasome activity, preventing pyroptosis, and thus increasing cell survival in dextran sulphate sodium (DSS)‐induced colitis mice." (PMID 39488745, 2024). "Moreover, as the possible metabolite of compound 4, coumaric acid, when combined with other anti-inflammatory compounds, could enhance the inhibitory effect on IL-1β release by NLRP3, thereby enhancing the drug’s ability to facilitate recovery from DSS-induced colitis in mice." (PMID 39202831, 2024).
colitis (continued). "The combination of Radix Astragali polysaccharides with CP polysaccharides in a mouse model of colitis could improve colitis symptoms in mice by elevating SOD, decreasing MDA to improve antioxidant activity, and simultaneously decreasing the expression of inflammatory factors TNF-α, IL-1β, and IL-6." (PMID 38803438, 2024). "In this study, we used ELISA to detect the contents of cytokines IL-1β, IL-6, TNF-α, IL-12, and TGF-β in mouse intestinal tissue, and we found that QYJD could significantly reduce the contents of IL-1β, IL-6, TNF-α, and TGF-β in colon tissue of mice with colitis." (PMID 36523417, 2022). "Moreover, the significance of oral pathobionts, but not gut pathobionts, to IL-1β secretion in the gut was confirmed, thus suggesting that IL-1β secretion in colitis may be attributed to oral pathogens." (PMID 34950607, 2021). "Moreover, MSC-derived exosomes alleviate colitis in vivo by inhibiting expression of IL-7 and inducible nitric oxide synthase (iNOS) in mouse colonic macrophages, thus limiting the production of nitric oxide and the expression of TNF-α, IL-6 and IL-1β and increasing IL-10 secretion." (PMID 32365813, 2020). "Furthermore, the serum TNF-α, IFN-γ, IL-1β, IL-6, and IL17 were significantly increased in the colitic mice, and hMSCs treatment could reduce these inflammatory cytokines, suggesting that hMSCs alleviated the inflammatory responses in colitis mice." (PMID 31367246, 2019). "The expression of the proinflammatory cytokines TNFα and IL-1β and iNOS gene (chosen as a marker of chronic inflammation) in the forepaws showed an increase in the “arthritis” group whereas no significant changes were observed in the “arthritis + colitis” group." (PMID 28926599, 2017). "However, the precise source of IL-1β producing cells in DSS colitis is currently not known." (PMID 23577872, 2013). "This subset has previously been observed in the mucosa of children with colitis, where CD8+ T cells can differentiate into non-classic Tc2 cells under stimulation with TGF-β in combination with IL-1β/TNF-α or IL-6, thus contributing to the disease." (PMID 40244207, 2025). "A decrease in intestinal macrophage and Th2 lymphocyte activity (decrease in IL-1β, IL-6, and IL-10 levels) was observed in the intestines induced by DSS in non-acute colitis (equivalent to non-acute UC), which was enhanced by SST-14 and OCT administration." (PMID 40508145, 2025). "Such animals produce reduced amounts of IL-1β and TNF and are protected from acute, but not chronic, experimental colitis." (PMID 41194916, 2025). "In IR62 treatment group, the all selected taxa, but not Muribaculum, exhibited a high correlation with all colitis-related markers except for TNF-α, IL-1β, iNOS, and occludin." (PMID 39849930, 2024). "In contrast, our study found that the differences in IL-1β expression levels in WT and mPGES-1−/− mice during TNBS-induced colitis were not statistically significant." (PMID 39596393, 2024). "We constructed a colitis mouse model with or without a C. difficile challenge using MCC950, which is a selective NLRP3 inflammasome inhibitor, to inhibit the production of IL-1β in vivo." (PMID 36951545, 2023). "As already mentioned in the “Cytokine” section, overexpression of IL-1β and IL-17, but not of TNF-α, has been demonstrated by two independent groups in samples from patients with ICI-induced colitis." (PMID 36900420, 2023). "The levels of IL-1β and TGF-β were slightly decreased in the RSV+Li01 group compared to other colitis mice group but exhibited no statistical difference." (PMID 35935130, 2022). "The results showed that the mRNA expression levels of Cgas, Il10, Cxcl10, Ifnb1, Tnf, Il6, and Il1b exhibited no obvious difference between GCV and vehicle treatment groups in DSS-colitis in STINGgt/gt mice (all p > 0.05)." (PMID 36467059, 2022). "In TNBS-induced colitis in mice, which resembles CD, NIN decreased ISMC hyperplasia as well as expression of TNFα and IL-1β, without effect in control animals." (PMID 35715562, 2022).
colitis (continued). "Our results suggest that chemogenetic inhibition of TRPV1+ neurons is not sufficient to reduce DSS-induced colitis, whereas CNO stimulation induces neurogenic inflammation in the colon, highlighted by TNF-α, IL-1β, or IL-6 upregulation." (PMID 34954381, 2022). "The researchers showed that NOR alleviated colitis and reduced the levels of NLRP3, cleaved caspase-1 and IL-1β in colons of the mice." (PMID 36090968, 2022). "By contrast, the expression of Il1β, Ifng, and TNF-α (Tnf) was significantly decreased by L. reuteri treatment during DSS-induced colitis (p < 0.05) without affecting Il6 or Il10 levels (p > 0.05)." (PMID 35320932, 2022). "Increased expression of pro-inflammatory cytokines, Il-1β, Il-6, and TNF-α, monocyte chemotactic protein-1 (Mcp-1) and macrophage inflammatory protein 2 (Mip-2), characterized DSS-induced colonic inflammation compared to non-colitic mice." (PMID 34072532, 2021). "Although IL-1β induced IL-33 expression in vitro, using Il1r1−/− mice, we showed this signaling pathway is not required for Il33 induction during DSS-induced colitis." (PMID 33953267, 2021). "In the current study, the decrease in inflammatory cytokines by Ala-Gln (not by Gln with IL-1β and TNF-α) indicated that the extent of colitis was ameliorated by Ala-Gln, which has better beneficial effects than Gln." (PMID 34046146, 2021). "We injected Gsdmd-/- mice with recombinant IL-1β and challenged these mice with DSS and found that recombinant IL-1β did not increase the severity of colitis but ameliorated the disease in Gsdmd-/- mice." (PMID 34721422, 2021). "IL-1β induces Il33 in colon myofibroblasts in vitro, but signaling through the IL-1R1 is not necessary for induction of IL-33 in DSS-induced colitis." (PMID 33953267, 2021). "Dex treatment strongly upregulated the expression of the cytokines TNFα, IL-1β and IL-6 but not IL-10 in the course of DSS colitis compared with that in the control group." (PMID 32290362, 2020). "In these mice, lack of KNG1 reduced colitis development, infiltration of inflammatory cells into the gut mucosa, and inflammatory cytokine levels (e.g., TNFα, IFN-γ, IL-1β, and IL-6)." (PMID 31623319, 2019). "Specifically, colitis enhanced mRNA levels of CD86 (t7.8 = −3.2; p = 0.013) and TNF-α (t9.3 = −3.4; p = 0.006), did not change IL-1β expression, but decreased Nos2 expression (t7.092 = 5.237; p = 0.001)." (PMID 31882991, 2019). "In the ileum, TNBS treatment markedly increased IL-1β and TNF-α mRNA abundances (P < 0.05), although matrine failed to mediate TNF-α expression in TNBS-induced murine colitis." (PMID 30800071, 2019). "However, we believe that contributions of pro-IL-1β and pro-IL-18 downregulation to colitis are none or negligible because impact of Rev-erbα on inflammasome activation (i.e., activation of caspase-1 and maturation of IL-1β) and experimental colitis is highly Nlrp3-dependent." (PMID 30315268, 2018). "Induction of colitis decreased MUC2 expression, which was reversed by administration of IL-18, but not IL-1β." (PMID 27966619, 2016). "The levels of IFN-γ, TNF-γ, IL-1β, IL-12p70 and IL-6, but not IL-10, were significantly higher in IL-21RKO mice than those in C57BL/6 mice on day 5 after DSS-induced colitis (*P < 0.05)." (PMID 27545302, 2016). "On the other hand, obestatin failed to affect mucosal IL-1β concentration and MPO activity in the colon of rats without induction of colitis." (PMID 26798415, 2016). "In this study, exogenous IL-1β reduced expression of colonic Th2 cytokines (IL-4 and IL-13) and improved OXA-induced colitis, while exogenous IL-18 also reduced severity of the colitis but without affecting expression of Th2 cytokines." (PMID 27966619, 2016). "Other cytokines (TNF-α, IL-1β, IL-6, IL-23, and IL-12p70) were detected in low levels and were not significantly different between the rIL-33- and PBS-treated mice with DSS colitis (data not shown)." (PMID 26161006, 2015).